CD4 (CD4 molecule)
Diseases named in the same sentence as CD4 in open-access papers (continued):
Sharing a sentence is not in itself a finding about the gene and the disease.
infection (continued). "Moreover, the immunized mice depleted of both CD4+ and CD8+ T cells failed to control infection and showed higher parasite burden, confirming liposomal EF1-α-protectively immunized mice were incapable of controlling challenge infection when both CD4+ and CD8+ T cells were depleted." (PMID 29441060, 2018). "This is perhaps not surprising: CD4 decline and SPVL are both temporal averages summarising virulence over a period of time, whereas GSVL is a single measurement typically taken at the beginning of infection (median time between date first positive and sample = 266 days)." (PMID 28604782, 2017). "We concluded that the observation that MmuPV1 infection could not be sustained in the anal mucosae of immunocompetent C57BL/6J mice, even under antibody depletion conditions, may have been due to insufficient CD4 T cell depletion." (PMID 29208932, 2017). "Although the relative contribution of CD4 T cells or antibody-secreting B cells has not been directly compared with CD8 T-cell activity, the critical importance of CD8 T cells in effective host immune responses during bacterial infection is convincing in murine infection models." (PMID 29259327, 2017). "On complete resolution of infection, the low dose of C. caviae did not alter the ratio of CD4+ and CD8+ cells within guinea pigs’ submandibular lymph node (SMLN) lymphocytes while the higher doses increased the percentages of CD4+ and CD8+ cells within the SMLN lymphocytes." (PMID 28678871, 2017). "An increase in the absolute number of circulating CD4+ T cells was observed prior to SIV infection in the macaques infected with SPgV, although a concomitant increase was also noted in the SPgV-naïve macaques during this time period, suggesting that this increase was not due to SPgV infection." (PMID 29073258, 2017). "Strong correlations were also observed between semen HIV-RNA load and the CD4+ cell count (r = -0.98, p<0.0001, adjusted p = 0.001), and the CD4/CD8 ratio (r = -0.85, p = 0.008, adjusted p = 0.10), while seminal RNA did not correlate with blood RNA and CD4 counts in recent infection." (PMID 28708873, 2017). "In all infection models reviewed herein, disruption of ICOS signaling led to poor CD4+ T cell Th2 polarization and diminished IL-4 production, which may or may not have been due to reduced expansion of CD4+ T cells in all cases." (PMID 27559335, 2016). "However, the frequency of Vα2 clonotypes in virus-specific donor CD4+ T cells declined quickly and homogeneously in all recipients transiently infected with F-MLV-N, whereas it remained very high in all recipients with non-resolving F-MLV-B infection." (PMID 26728651, 2016). "Combined, these data indicate that upon egress from the spleen, CD4+ YFP+ GFP+ T cells can seed the nonlymphoid organs during malaria infection and that rapid in situ reprogramming of CD4+ YFP+ GFP− T cells does not appear to occur within nonlymphoid tissues during infection." (PMID 26459508, 2016). "In CD4+ T cell-depleted animals, the viral titers in organs were slightly elevated at day 13 p.i. compared to CD8-/-JHT animals, indicating that the control of the infection during simultaneous absence of CD8+, CD4+ and B cells is not as effective as in CD8-/-JHT mice." (PMID 25658831, 2015). "Furthermore, we observed CD4+T cell-mediated control of HTNV replication during early, but not late infection, as both IFN-γ secretion from CD4+T cells and peak HTNV viremia were observed during the febrile stage, followed by a gradual decrease throughout the follow-up period of the disease." (PMID 25836633, 2015). "The course of total cytotoxic T lymphocytes (CD4–CD8α+high cells: 2.5 × 103 cells/μL) as well as of total and activated NK cells (CD3–CD8α+ cells: 1.4 × 103 cells/μL; CD3–CD16+ cells: 1.2 × 103 cells/μL) were not influenced by PCV2 natural infection in vaccinated and unvaccinated animals." (PMID 24735253, 2014).
infection (continued). "However, at the lowest level of CD4 expression, increasing CCR5 levels could partially rescue infection by YU-2 (10 fold increase) but not ZM247F." (PMID 24656066, 2014). "While sham-immunized mice died at day 6 after infection and largely failed to recruit either CD4+ T helper cells or VV-specific CTLs into the CNS compartment, MVA immunized animals harbored both antigen specific CTLs and CD4+ T cells in the CNS and recovered from VV encephalitis." (PMID 24606807, 2014). "Indeed, ERE-specific T cells failed to expand anamnestically in vivo following infection with SIVsmE660 and did not recognize SIV-infected targets in vitro, in agreement with no significant induction of targeted ERE mRNA by SIV in macaque CD4+ T cells." (PMID 24651676, 2014). "Infected primary CD4+ T cells, as well as Jurkat and CEM-ss cells, showed no consistent differences in ECAR and OCR upon provision of galactose compared with uninfected cells, suggesting that oxidative metabolism of T cells is not grossly altered upon infection with HIV-1." (PMID 25421745, 2014). "We have previously shown that infection with Plasmodium berghei NK65 infection, the non-cerebral malaria pathological agent, renders the thymus atrophic through the enhanced thymocyte death by apoptosis and premature egress of CD4+CD8+ (Double-positive, DP) T cells to the periphery." (PMID 25329161, 2014). "IL-27 limits IFN- γ production by CD4+ T cells during various infections, attenuates the development, but not necessarily maintenance, of Th17 responses by limiting retinoid-related orphan receptor (ROR)c expression and stimulates IL-10 production by multiple effector CD4+ T cell populations." (PMID 23593003, 2013). "Interestingly, TRAIL mediated CD4 T cell apoptosis did not require productive infection, and TRAIL expressing pDC were reported to be unable to lyse HIV-1 infected CD4 T cells possibly favouring the depletion of uninfected CD4 T helper cells in the face of CD4 T cell viral reservoirs preservation." (PMID 24455433, 2013). "As we, and others, have shown an important role for IL-10 in limiting immunopathology during malaria infection, we determined whether elevated T-bet expression by effector CD4+ T cells and increased Th1 cell terminal differentiation in WSX-1−/− mice during infection was due to lack of IL-10." (PMID 23593003, 2013). "Reduced vDNA in PBMC did not appear to be a result of decreased CD4+ PBMC levels, as changes in PBMC vDNA levels did not reflect the multiple log reduction in plasma viremia observed in the treated animals and in some untreated animals that spontaneously controlled infection." (PMID 24367650, 2013). "BrdU staining of pulmonary CD4+ and CD8+ T cells from CBA/J mice was not dramatically altered throughout infection, suggesting that the increased numbers of CD8+ T cells that were evident in CBA/J mice may not be due to local proliferation, but a consequence of enhanced cellular recruitment." (PMID 23472214, 2013). "In contrast to MHCII−/− mice, not only lacking CD4 T cells but also IgG antibodies, CD4−/− mice, a mouse strain that is able to support immunoglobulin class switching, were able to eventually control MCMV replication in the salivary gland approximately 6 months post infection." (PMID 23717308, 2013). "In contrast, following infection of C57BL/6 mice with the L. major strain NIH/Sd, which produces nonhealing dermal lesions in a Th1-polarized setting, it was shown that IL-10-producing CD4+ CD25− FoxP3− Th1 cells rather than Treg cells are the major contributors to immune suppression." (PMID 23825956, 2013). "Depletion of CD8+ T cells, but not CD4+ T cells, using monoclonal antibodies accelerates the mortality of mice chronically infected with T. gondii, which provides support for the role of CD8+ T cells in controlling the parasite during the chronic phase of the infection." (PMID 24741372, 2013).
infection (continued). "Moreover, as HTLV-1 preferentially affects CD4+ T cells, the migration of non-infected CD4+ T cells to inflamed sites containing HTLV-1-infected lymphocytes could facilitate cell-cell contact and consequently the spread of infection." (PMID 23284797, 2012). "Furthermore, the similar extent of depletion of not only naïve CD4+ T cells but also naïve CD8+ T cells that are not usually infected by HIV, suggests that there is a general mechanism impacting naïve T cell populations unrelated to direct infection." (PMID 22241988, 2012). "Provision of additional T cell help by adoptive transfer of tg CD4+ T cells was not sufficient to rescue the poor endogenous CD8+ T cell response in old, Tx and MCMV-infected mice although CD8+ T cell expansion after VACV-GP infection is known to be help dependent." (PMID 22916013, 2012). "Thus, such cross reactive CD4 and CD8 T cell responses may not be very effective for protection against infection and pathogenesis by H5N1 HPAIV." (PMID 22859976, 2012). "Specifically, in the absence of infection, CD4+ and CD8+ T cells maintain close to one million cells/MLN in WT and CD118−/− whereas following 100 PFU/cornea HSV-1, similar levels (2-3 million) of CD4+ and CD8+ T cells were isolated from the MLN of WT and CD118−/− mice 6 d PI." (PMID 21709805, 2011). "In addition, while CD4+CD25−effector cells from mice with an acute infection exhibited a strong proliferative response in vitro to SEA, CD4+CD25+Tregs taken at the chronic stage of infection did not proliferate." (PMID 21858239, 2011). "Data show that these clusters were massive (>100 μm), composed of both CD4+ and CD8+ T cells (but not B cells) and were usually found around L.m-infected CD11c+ cells, similar to what was recently described during the secondary challenge infection against Toxoplasma gondii in LNs." (PMID 20634957, 2010). "However, de novo infection in the absence of CD4 help has been shown to generate defective CD8 T cell memory, and the degree of CD4 dependence may vary with the pathogen." (PMID 20181071, 2010). "Idiopathic CD4+ lymphocytopenia, described in 1992 by the Centers for Disease Control, is characterized by persistent CD4+ lymphocytopenia (less than 300 cells per micro-liter) in nonimmunosuppressed, HIV negative individuals, who present with atypical infections." (PMID 20806085, 2010). "In mice that lacked CD4+ T cells during the primary response, the memory pool of CD8+ T cells was initially similar in size and functionality to that seen in wild-type mice but began to decline after longer intervals, leading eventually to the recrudescence of the infection." (PMID 16494717, 2006). "Given the unique immune profile of the Case, with a specific absence of activated CD4+ and CD8+ T lymphocyte subpopulations in the peripheral blood, it is plausible to consider that these cells may be homing to specific tissues in response to signals of infection or damage." (PMID 39871364, 2025). "On the other hand, we showed that CD4+ TEMRA do not increase their mitochondrial membrane potential as drastically as CM and EM cells upon anti-CD3 stimulation, which suggests that their mitochondrial capacity is impaired and may affect responses to infection in the elderly." (PMID 37106796, 2023). "A clear increase in the effectiveness of both CD4 and CD8 T cell control could be seen in the absence of pUL11, as indicated by a greater reduction in the virus spread in HCMV Merlin dUL11 GFP-infected cultures than in HCMV Merlin GFP infections in the presence of CD4 or CD8 T cells." (PMID 36445084, 2022). "We did not study the capacity of the vectors to prime CD4+ T cell responses, but it would be interesting to determine whether the differences in CD8+ T cell priming are due to CD4+ helper T cell skewing from differential functional activation of DCs after infection." (PMID 34811393, 2021).
infection (continued). "Similarly, CD4+ T-cells from wP-vaccinated animals secreted IFN-γ but no IL-5; IL-17 secretion was between levels for naïve and convalescent baboons, suggesting that wP vaccination induces similar, albeit weaker, Th1 and Th17-memory responses to natural infection." (PMID 34452002, 2021). "Interestingly, animals with MOG35–55-specific CD4+ T cells (2D2 mice) display a higher incidence of spontaneous EAE disease following influenza respiratory infection when compared with noninfected mice, suggesting that the peripheral infection can trigger CNS immunosurveillance and disease." (PMID 31725411, 2020). "Moreover, CD4+ T cells plus non-T lymphocytes and accessory cells derived from the same donor mice or reconstituted in the same HCT recipients did not confer or mediate protection, which suggests that CD8+ T cells are the only antiviral effector cells that control the infection in the recipients." (PMID 30563202, 2018). "And we were also able to demonstrate in vitro that hepatic CD4+LAG3+ T cells and CD8+2B4+ T cells actually displayed impaired effector phenotype, indicating altered functions of both subpopulations of T cells in mice which could not clear infection because of high PSC inoculum." (PMID 28894272, 2017). "Finally, the number of HSV-2 infected cells required for a cytolytic T cell response to infection was estimated to be lower in men with HIV and CD4+ T-cell count>500/μL versus HIV negative men: this may suggest impaired antigen presentation in patients with HIV." (PMID 27285483, 2016). "However, much emphasis has been placed on trans-infection, a mechanism where DCs capture HIV-1 through C-type lectins, mainly Dendritic Cell-Specific Intracellular adhesion molecule-3-Grabbing Non-integrin (DC-SIGN), and transfer the virus to CD4+ T-lymphocytes." (PMID 25793526, 2015). "However, CD8+ T-cell responses to infectious pathogens are different, in that infections generally incur severe inflammation and T-cell activation and in that some of these antigens actually can induce the primary expansion of the specific CD8+ T cells without CD4 help." (PMID 26272364, 2015). "Finally, whilst recent studies do not support high frequencies of DC infection, due to the direct consequence of DC expressing the HIV restriction factor SAMHD1, the majority of data to date observe only limiting numbers of infected DCs being readily capable of rapidly seeding CD4 T cell infections." (PMID 22685410, 2012). "However, for CD4+ cells generated in the absence of I-Ab molecules, a two-fold increase in CD69 expression was already observed in non-infected mice (compared to non-infected WT mice), which is a known feature of NKT cells, and infection led to additional augmentations of these values." (PMID 21814579, 2011). "Infection of NP-2/CD4/CCR5 cells with CBL23 and mndGB-1, but not with the GUN-7WT or HCM342 strains, was also partially blocked by the peptide, suggesting that the fMLF peptide may have inhibitory effects on infection of CCR5-positive cells by several strains of HIV/SIV." (PMID 18577234, 2008). "In addition, while the AIM assay provides a very sensitive method to quantify spike-specific CD4+ and CD8+ T cells, we did not analyze T-cell functions such as cytokine production or proliferation that could reveal differences in the effector activity of vaccine- or infection-induced responses." (PMID 38035132, 2023).
cancer (4,820 papers, 1990 to 2026). A tumor composed of atypical neoplastic, often pleomorphic cells that invade other tissues. "High levels of CD4 + Th1 cells that express IFN-γ in the blood are associated with a positive response to cancer." (PMID 41582199, 2026). "All these findings support the observation that a CD4+ Th1-associated immune signature in the TME is associated with positive prognostic markers in several human cancers." (PMID 40543509, 2025). "We previously reported a naturally occurring CD4+ T cell response against hTERT in several cancers, including NSCLC, and this presence was associated with a good prognosis." (PMID 40543509, 2025). "This analysis identified 522 genes whose expression during CD4+ T cell activation has potential effects on pan‐cancer risk using a strong instrument approach and identified 23 additional effects that were validated using five or more weak instrument methods." (PMID 41216857, 2025). "Impaired immune function caused by some pathogenic infections, cancers, chemotherapeutic treatments, or immunosuppressive therapies results in a depletion of CD4+ T cell populations." (PMID 40016189, 2025). "Using eight conventional MR and colocalization methods, we estimated effects of 11 021 dynamic gene expression profiles during CD4+ T cell activation on the risk of six cancer types." (PMID 41216857, 2025). "CD4+ T cells contribute to antitumor immunity and are implicated in the efficacy of cancer immunotherapies." (PMID 39782693, 2025). "Studies have highlighted that low CD4 (<200 cells/mm3) count and high viral load (>500 copies/mL) increase the risk of almost all cancer." (PMID 39869644, 2025). "The infiltration of CD3+, CD8+, and CD4+ T cells is associated with a favorable prognosis, whereas that of FOXP3+ regulatory T cells (Tregs), an immunosuppressive subset of CD4+ T cells, is associated with a poor prognosis in several cancers." (PMID 39679910, 2025). "Evaluation of the cancer–immunity cycle revealed that the low-risk group exhibited higher activity in key steps including CD4+ T cell recruitment, Th17 cell recruitment, and immune cell infiltration into tumors." (PMID 41383634, 2025). "Consistent with the findings from the mouse model, ICOS upregulation in CD4+ T cells was associated with later irAE incidence in patients with cancer." (PMID 40198121, 2025). "In a multicentre cohort of PLWHIV with viral suppression for more than two years, higher time-updated CD4 counts were linked to significantly lower cancer incidence—adjusted incidence rate ratios declined from 1.0 at <350 cells/μL to 0.26 at ≥750 cells/μL." (PMID 41295583, 2025). "High-MS group exhibited elevated neutrophil infiltration (p = 0.00067), cancer-associated fibroblasts (CAFs) activity (p = 1e-08), memory B cells (p = 4.2e-06), and CD4 + T cells (p = 0.004), suggesting its potential resistance to immunotherapy." (PMID 40694220, 2025). "CXCL8 derived from cancer-associated adipocytes shows a synergistic effect on anti-tumor immune response by inducing CD4+ T cell and CD8+ T cell infiltration and upregulating CD274 expression." (PMID 40863244, 2025). "The correlation matrix showed that SPOP expression was significantly positively associated with the recruitment of CD8+ T cells, CD4+ T cells, and Th1 cells, while negatively correlated with T cell recognition of cancer cells." (PMID 40657370, 2025). "The increased cancer risk remained when accounting for CD4 cell count, suggesting an effect of HIV-1 viremia on the risk of developing these cancers that is not mediated by cellular immunodeficiency." (PMID 39736138, 2025). "We used gene expression data of CD4+ T cells derived from whole blood as exposures to identify the cancer‐linked genes." (PMID 41216857, 2025). "We found in GBMLGG, IGSF8 expression levels were negatively associated with cancer associated fibroblasts (CAFs), macrophages, NK cells and positively associated with B cells and CD4+ T cells." (PMID 40936932, 2025).